MCL1 (MCL1 apoptosis regulator, BCL2 family member)
Diseases named in the same sentence as MCL1 in open-access papers (continued):
Sharing a sentence is not in itself a finding about the gene and the disease.
hematological malignancies (continued). "While preclinical studies using combined treatment with venetoclax and MCL-1 inhibitors in hematological malignancies has generated a substantial enthusiasm for overcoming venetoclax resistance, clinical evaluations appear to reveal excessive toxicity of such regimens." (PMID 33799470, 2021). "In addition, we discuss the use of MCL-1 selective inhibitors in different hematologic malignancies and solid tumors." (PMID 33883020, 2021). "Previous studies showed that hematological malignancies are highly dependent on MCL-1." (PMID 33308268, 2020). "The antiapoptotic protein MCL-1 is an irrefutable therapeutic target in hematologic malignancies." (PMID 32183335, 2020). "Indeed, the scientific community expects that the current clinical evaluation of these MCL-1 BH3 mimetics in hematologic malignancies will result in at least one of them being clinically approved." (PMID 32183335, 2020). "New BH3 mimetics, including MCL-1 targeted compounds, are currently under clinical trials and might provide valuable new options for patients with hematologic malignancies." (PMID 32183335, 2020). "Rationale and progress in targeting Mcl-1 in hematologic malignancies have been recently reviewed." (PMID 32455818, 2020). "In addition, we examined the changes in GBP2, BAK, and MCL-1 protein levels following exposure to the main chemotherapeutic agents used for the treatment of hematological malignancies, including doxorubicin, cytarabine, vincristine, etoposide, and interferon-γ." (PMID 34294680, 2021). "This review focuses primarily on hematologic malignancies because they exhibit pronounced transcriptional addiction to short-lived super-enhancer-driven transcripts (MYC, MCL-1), making CDK9 inhibition particularly effective." (PMID 42201387, 2026). "By targeting a central regulator of transcriptional elongation, this approach selectively disrupts the sustained expression of survival-critical proteins such as MCL-1 and MYC, thereby exposing a therapeutic vulnerability in hematologic malignancies." (PMID 42201387, 2026). "The effects of CDK9 have been studied in hematologic malignancies, and many of them have suggested the downregulation of master transcription factor MYC or upregulation of anti-apoptotic molecules such as MCL1 and BCL2." (PMID 40713627, 2025). "The therapeutic potential of MCL1 inhibitors, both as monotherapy and in combination with BCL2 inhibitors like venetoclax, is being explored in various hematologic malignancies." (PMID 40075071, 2025). "Other Mcl-1-specific BH3 mimetics (AMG-176, AMG-397 and AZD-5991) have entered clinical evaluation for patients with hematological malignancies." (PMID 38542429, 2024). "The Mcl-1 inhibitor PRT1419 is being investigated for the treatment of patients with relapsed and/or refractory hematologic malignancies (NCT04543305, clinical phase I)." (PMID 37371761, 2023). "The high pro-apoptotic efficacy of MCL-1 and BCL-2/BCL-XL co-inhibition was also found in previous studies concerning hematological malignancies and solid tumors." (PMID 37108344, 2023). "All three direct inhibitors of Mcl-1, e.g. AMG-176, have been tested in the clinic for hematological malignancies." (PMID 35273915, 2022). "Maritoclax selectively inhibits the proliferation of leukemic cells with high MCL-1 expression and significantly enhances the therapeutic effect of ABT-737 on various hematological malignancies." (PMID 33883020, 2021). "Two other MCL-1 inhibitors AZD-5991520 and AMG-176521 have also entered clinical trials to evaluate their safety, PKs, and antitumor response in patients with hematological malignancies (NCT03218683 and NCT02675452)." (PMID 34054126, 2021). "This miRNA cluster regulates, at the post-transcriptional level, different oncogenes including the myeloid cell leukemia 1 (MCL1) and the B cell CLL/B cell lymphoma 2 (BCL2), which exert an oncogenic function in this hematological disorder." (PMID 32182763, 2020).
hematological malignancies (continued). "Several other MCL-1 inhibitors [AZD5991(AstraZeneca), AMG-176, AMG-397(Amgen), S64315/MIK665(Novartis)] are currently undergoing phase I clinical trials in a variety of hematological malignancies." (PMID 32131385, 2020). "Here we found that the MCL1-inhibitor S63845 and the MEK-inhibitor trametinib have target specificity for primary cells of hematological malignancies with elevated MCL1- and MEK-protein levels." (PMID 31718075, 2019). "While MCL-1 inhibitors are being evaluated in various hematological malignancies, selective BCL-XL inhibitors have not yet entered clinical trials." (PMID 37945692, 2024). "AMG 176 caused reductions in B cells, monocytes, and neutrophils in human MCL1 knock-in mice, and may provide therapeutic promise in models of AML as well as other hematologic malignancies." (PMID 38256213, 2024). "Nevertheless, the role of the Akt signaling pathway possibly by upregulation of non-Bcl-2 antiapoptotic proteins such as MCL-1 and Bcl-XL in the development of venetoclax resistance has been confirmed in hematologic malignancies." (PMID 39035053, 2024). "In this regard, ABT-199, S63845 (MCL-1 inhibitor), and A-1331852 (BCL-xL inhibitor) have been described to affect ∆ψm in hematological malignancies accompanied by swollen mitochondria, rupture of the mitochondrial outer membrane as well as loss of cristae structure." (PMID 37210688, 2023). "This effective co-inhibition of BCL-2 and MCL-1 using BH3 mimetics was previously reported in hematological malignancies but not RMS." (PMID 35393436, 2022). "Moreover, reports showing MCL-1 and BCL-2 co-inhibition is tolerated in mice, and is synergistic in hematological malignancies, are starting to emerge." (PMID 31019203, 2019). "ABT-737 and its orally bioavailable analogue ABT-263 are potent, selective small-molecule inhibitors of Bcl-2 and Bcl-Xl, but not Mcl-1, showing potent clinical activity towards several hematological malignancies." (PMID 25008202, 2014). "Collectively, a novel redox-dependent mechanism of Mcl-1 stability is demonstrated for the acquisition of VEN resistance, which has therapeutic implications for employing redox modulating strategies and AKT inhibitors against VEN-resistant hematologic malignancies." (PMID 40707672, 2025). "Notably, several highly specific myeloid cell leukemia 1 (MCL1) inhibitors have recently entered clinical trials for various hematologic malignancies, although not for CML, reflecting the insensitivity of CML cell lines to single MCL1 inhibition." (PMID 34564697, 2021). "Furthermore, our data reveal that baseline expression of BCL‐2, BCL‐xL or MCL‐1 were not predictive of sensitivity to the BH3‐mimetics tested, similar to studies in hematological malignancies and solid tumors." (PMID 31228231, 2019). "Additionally, we did not observe any change in the expression of MCL1 (data not shown), another validated BRD4 target in hematological malignancies." (PMID 25537515, 2015).
hematological cancers (36 papers, 2015 to 2025). "While VEN triggers apoptosis in Bcl-2-dependent hematological cancers, other anti-apoptotic proteins such as Mcl-1 or Bcl-xL appear to play an important role(s) in VEN responsiveness." (PMID 40707672, 2025). "Previous studies revealed that CDK9 inhibitors induce apoptotic cell death, reducing the expression level of MCL1 in hematological cancers." (PMID 40713627, 2025). "Inhibition of Mcl‐1 has been shown to potentiate the anticancer effect of an HDAC inhibitor (panobinostat) in models of hematological cancer." (PMID 40483575, 2025). "A previous study revealed that MCL-1 plays a pivotal role in regulating fatty acid oxidation (FAO) pathway proteins independently of its anti-apoptotic function in MCL-1-driven hematologic cancer cells." (PMID 38706892, 2024). "Other Mcl-1 inhibitors under active consideration for use in RRMM as well as other hematologic cancers include S-64315/MIK665 (NCT02992483), PRT1419 (NCT04543305), and AZD-5991 (NCT03218683)." (PMID 36768967, 2023). "In this study, we discovered that BAPTAi alone induced apoptosis in hematological cancer cell lines that were highly sensitive to S63845, an MCL-1 antagonist." (PMID 37684238, 2023). "MCL-1 has also emerged as an important resistance factor to BCL-2/BCL-XL specific BH3-mimetics in hematopoietic cancers, encouraging the investigation of combinatorial treatments to also target MCL-1." (PMID 35349392, 2022). "Pharmacologic inhibition of MCL-1 has already been presented as a good strategy to improve VEN efficacy in various hematological cancers, however, important safety concerns have been recently raised." (PMID 35091682, 2022). "For targeting Mcl-1, two Mcl-1 inhibitors are currently being evaluated in ongoing phase I/II clinical trials for different hematological cancers, namely PRT1419 and S64315 (MIK665)." (PMID 36293331, 2022). "One such molecule is S63845, which has demonstrated preclinical monotherapeutic activity in diverse hematologic cancers as a consequence of the disruption of MCL-1 complexes." (PMID 34065859, 2021). "We will now discuss the findings supporting the implication of MCL-1 in an array of solid and hematological tumors and review the potential combinations of MCL-1 inhibitors with preexisting therapeutic options." (PMID 33308268, 2020). "In recent years an increasing interest in developing a Mcl-1-specific inhibitor is arising, especially for hematological tumors." (PMID 32455818, 2020). "These available reports suggest that hematological cancer cell survival is Bcl-2-dependent, whereas solid cancers typically depend more on Mcl-1 for their survival." (PMID 26009874, 2015). "Pro-survival molecules were shown to be involved in the microenvironment-induced response of hematological cancer as shown for MCL-1-mediated survival of CLL cells in bone marrow stromal microenvironment." (PMID 26035829, 2015). "To validate this hypothesis, we utilized the GDSC database, which includes 18 TNBC cell lines tested for their response to a different MCL1 inhibitor called AZD5991 that entered clinical trials for hematologic cancers." (PMID 38762181, 2024). "Moreover, protein myeloid cell leukemia-1 (Mcl-1) is overexpressed in multiple myeloma, acute myeloid leukemia and several hematologic cancers that make up the NHL." (PMID 38731446, 2024). "In addition, not only hematological cancer cell lines but also normal B lymphocytes are sensitive to BAPTAi, which correlates with their sensitivity toward MCL-1 inhibition." (PMID 37684238, 2023). "Mcl-1 is considered as the primary venetoclax-resistant factor and inhibition of Mcl-1 could reverse venetoclax resistance in various hematologic cancers." (PMID 36658493, 2023). "MCL-1 was shown as one of the key mediators of resistance to VEN in various hematological cancers." (PMID 35091682, 2022).
hematological cancers (continued). "Importantly, combinatorial targeting of BCL-2 and MCL-1 is tolerated in mice and is under investigation in clinical trials of hematological cancers (NCT03672695, NCT04702425)." (PMID 35349392, 2022). "MCL1 overexpression has been reported in some hematological cancers and solid tumors." (PMID 32527042, 2020). "While MCL-1 BH3 mimetics are advancing into clinical trials either alone or with venetoclax in hematological cancers, it remains uncertain whether these drugs will be able to sufficiently block the interaction of MCL-1 and proapoptotic BH3-only proteins such as NOXA and BIM." (PMID 33589591, 2021). "Amgen’s MCL-1 inhibitor, AMG 176, was also demonstrated to have preclinical activity across several hematological cancers as well as combination activity with traditional chemotherapeutics." (PMID 34065859, 2021). "In the same study, 2-DG rapidly affected steady-state MCL-1 levels, sensitizing human hematopoietic tumor cell lines to ABT-737, a nonselective BCL-2/BCL-XL-antagonizing BH3 mimetic." (PMID 37684238, 2023). "BAPTAi alone induced cell death especially in MCL-1-dependent hematological cancer cells, but not in those cells not addicted to MCL-1." (PMID 37684238, 2023). "However, the reduction in Mcl-1 expression is not sufficient for initiating cell death in hematopoietic cancer cells with high Bcl-xL expression." (PMID 28038464, 2017).
blood cancers (9 papers, 2016 to 2023). "In this study, we have identified factors (loss of BAX; gain of BCL-XL and/or A1) that confer resistance to the new class of BH3-mimetics targeting MCL-1, drugs which are currently being evaluated in clinical trials for diverse blood cancers." (PMID 36755070, 2023). "A variety of MCL-1 inhibitors are now undergoing clinical trials for blood cancer treatment and application of this new class of drugs is also being tested in solid cancers." (PMID 35349392, 2022). "Agents worth testing in combination studies include FLT3 inhibitors in AML, BCR signaling inhibitors in certain NHL subtypes, and BH3 mimetic drugs (BCL2 inhibitor venetoclax and MCL-1 inhibitors) in a variety of blood cancers." (PMID 34408976, 2021). "It seems that miR-29 plays a vital role in blood cancers by modulating T-cell leukemia/lymphoma protein 1 (TCL1), myeloid cell leukemia 1 (MCL1), and DNA-methyltransferase enzymes." (PMID 36064322, 2022). "We and others have demonstrated that Mcl-1 plays an important role in the antileukemic activity of the Bcl-2-selective inhibitor ABT-199 in AML and other blood cancer cells." (PMID 27166183, 2016).
bacterial infection (6 papers, 2013 to 2025). "Our findings suggest Mcl-1 and cFLIP safeguard mRNA translation in DCs and highlight differences in how macrophages and DCs employ PRRs and guard proteins to respond to bacterial infection." (PMID 40530878, 2025). "The level of Mcl-1 rapidly increased within 2 h after bacterial infection, reached a maximum at 6 h, and then remained elevated for up to 24 h." (PMID 23431241, 2013). "Since STAT3 is responsible for MCL-1 upregulation at 72 hpi and is vital for bacterial infection, we evaluated whether STAT3 activation is an essential component of apoptotic inhibition by E. chaffeensis." (PMID 41115066, 2025). "Further, we used SwissTargetPrediction to predict that its main targets are ALOX5, MCL1, and SLC6A4, and find that it can inhibit bacterial biofilm formation and reduce bacterial infection of cells." (PMID 37275170, 2023). "In pathogen-engaged neutrophils, the RNA-destabilizing protein tristetraprolin (TTP) regulates apoptosis during bacterial infection by binding to the ARE elements at the MCL1 3′ UTR, destabilizing MCL1, and decreasing MCL1 expression." (PMID 29361709, 2018).
cardiovascular disease (4 papers, 2015 to 2022). "Other seed genes, such as FOS, SOCS3 and MCL1, should also be mentioned due to their special clinical value in cardiovascular diseases." (PMID 34271875, 2021). "Other seed genes, such as FOS, SOCS3 and MCL1, may also be potential targets for treatment due to their special clinical value in cardiovascular diseases." (PMID 34271875, 2021). "Therefore, pharmacological activation of Mcl-1 in the heart could induce mitophagy to protect myocytes from cell death activation and prevent cardiovascular disease development." (PMID 35563775, 2022).
heart disease (3 papers, 2014 to 2023). "Due to the cardio-protective role of Mcl1, delivery of Mcl1 3′-UTR is an effective therapeutic strategy for heart diseases." (PMID 33469534, 2020). "Due to the cardiac-protective role of Mcl1, to increase Mcl1 level is a prominent candidate for cardiac disease therapy." (PMID 33469534, 2020).
nervous system tumors (2 papers, 2018 to 2024). "In this study, we found that interference with Usp9X, a deubiquitinating enzyme which is overexpressed in nervous system tumors, or Mcl-1, an anti-apoptotic member of the Bcl-2 family whose degradation is regulated by Usp9X, causes rapid death in human MPNST cell lines." (PMID 30478285, 2018).
neurologic disease (2 papers, 2021 to 2025). "Recent research has revealed the critical role of the ubiquitination (Ub) process of MCL‐1 in regulating neuronal survival, offering a new perspective for treating neurologic diseases associated with cell death." (PMID 39764629, 2025). "MCL-1 protein abundance was reduced in eif2b5-mutant mouse model of the leukodystrophy vanishing white matter disease (VWMD), suggesting the potential for MCL-1 deficiency to contribute to clinical neurologic disease." (PMID 34873168, 2021). "MCL1 has the ability to switch between autophagy and apoptosis functions under conditions of energy stress in a developmental regulatory manner, and literature reports suggest it may be an important target for neurological diseases." (PMID 39764629, 2025).
gynecologic tumors (1 paper, 2023). "JOSD1 promotes chemoresistance by stabilizing MCL1 in gynecologic tumors." (PMID 38012642, 2023).
inflammation (1 paper, 2019). Aberrant reaction of the microcirculation characterized by movement of fluid and leukocytes from the blood into extravascular tissues. "AT7519 has also been shown to improve LPS-induced pulmonary inflammation resolution through downregulation of Mcl-1." (PMID 30886578, 2019).
kidney disease (1 paper, 2010). "Neither MCL1 nor IER3 have been studied in the context of primary GN, and further studies will be necessary to better define their role in kidney disease." (PMID 20976140, 2010).
MCL1 also shares sentences with these, for which no sentence is quoted: adenocarcinoma (5 papers); B-cell acute lymphoblastic leukemia (3); breast (3); cutaneous melanoma (3); fibrosarcoma (3); malignant pleural mesothelioma (3); colorectal adeno-carcinoma (2); hemorrhage (2); immune dysfunction (2); infantile hemangioma (2); infectious disease (2); Insulin resistance (2); lymphocytic leukaemia (2); marginal zone lymphoma (2); neurodegenerative disease (2); oral cavity tumors (2); Type 2 diabetes (2); -neck cancer (1); airway allergy (1); amyloid (1); anal carcinoma (1); anaplastic astrocytoma (1); and sensory neuropathy (1); angiosarcoma (1); aristolochic acid nephropathy (1); astrocytoma (1); Atopic Dermatitis (1); atypical teratoid rhabdoid tumor (1); benign tumors (1); biliary tract cancer (1).
A further 74 diseases each share a sentence with MCL1 in 1 paper.